CRP (C-reactive protein)
Diseases named in the same sentence as CRP in open-access papers (continued):
Sharing a sentence is not in itself a finding about the gene and the disease.
infection (continued). "Inflammatory cytokines such as interleukin-6 (IL-6), C-reactive protein (CRP), and procalcitonin (PCT) have clinical significance as predictive or prognostic markers of infection." (PMID 32711473, 2020). "C-reactive protein and white cell count (WCC) are the most commonly used markers of postoperative inflammation and infection." (PMID 32104193, 2020). "C-reactive protein (CRP) and procalcitonin (PCT) can help clinicians to diagnose surgical infections." (PMID 32070390, 2020). "We found that CRP (mg/dL), PCT (ng/mL), lymphocyte percentage, NLR, PLR, SLEDAI 2K and SDI from the combined groups with infection were significantly higher than those of the combined groups without infection." (PMID 33199770, 2020). "Most of the surgeons use CRP, ESR and WBC as the marker of eradication of infection prior to perform the second stage of surgery." (PMID 32296477, 2020). "Inflammation and infection play a vital role in the process of developing PJI and various markers related to these processes such as the C-reactive protein (CRP) and erythrocyte sedimentation rate (ESR) have been investigated for their ability to predict PJI." (PMID 33028348, 2020). "Multiple logistic regression analysis showed that elevated levels of MRP8/14 (log10 OR = 5.5, 95% CI = 3.1–9.6), CRP (log10 OR = 2.4, 95% CI = 1.3–4.1), and HNE (log10 OR = 2.3, 95% CI = 1.3–4.0) were predictive of acute KD over an infection (p < 0.001)." (PMID 32775314, 2020). "The level of C-reactive protein (CRP) was tremendously higher in over-70 patients (P<0.001), indicating a more serious infection." (PMID 33106442, 2020). "CRP belongs to the family of soluble proteins that are involved in the acute phase reaction (APR) to injury, damage, or infection." (PMID 32150980, 2020). "During inflammatory events, where CRP varies by up to ∼100-fold, the SAA response was consistent across subjects, increasing by up to 1000-fold over baseline in major infections." (PMID 32253915, 2020). "C-reactive protein (CRP), a circulating acute-phase plasma protein, increases very rapidly and at high serum concentrations in response to infection or tissue injury." (PMID 32983135, 2020). "The difference between the induction of CRP and LRG expression in fetal hepatocytes highlights the utility of LRG as a marker for detecting fetal infection." (PMID 33211747, 2020). "These four predictors (current smoking, CRP, pleuritic pain and platelet count) remained after adjusting the model for demographic variables, PSI, and extent of infection." (PMID 32906593, 2020). "The proportions of patients with high hs-CRP were 43% and 47% in the PROVE-IT (Pravastatin or Atorvastatin Evaluation and Infection Therapy) trial and IMPROVE-IT (Improved Reduction of Outcomes Vytorin Efficacy International Trial) trial, respectively." (PMID 32544081, 2020). "Our most important finding was that a combined measurement of MRP8/14 and CRP, and possible HNE, was indicative of KD, discriminating KD from probable infections in febrile children." (PMID 32775314, 2020). "Markers like C-reactive protein (CRP) and procalcitonin (PCT) are often considered to indicate infections and they are discussed as biomarkers in FN." (PMID 32519027, 2020). "The utility of traditional markers (e.g., CRP, ESR, PCT) for detecting infection in SLE patients has been discussed for several decades." (PMID 33199770, 2020). "Blood leucocyte counts, C-reactive protein (CRP) and procalcitonin (PCT) are the most widely used biomarkers of infection used in current practice." (PMID 32690014, 2020). "Few other studies also showed positive correlation between CRP, TLC with serum creatinine which indicates that infection has a role in developing AKI." (PMID 32968287, 2020). "Although C-reactive protein (CRP) and white blood cell (WBC) count are popular in Middle-Eastern countries for infection monitoring and are performed on daily or twice weekly basis, no laboratory test has been found reliable for this indication." (PMID 32257148, 2020).
infection (continued). "Similar to the short pentraxin CRP, the serum amyloid A (SAA) proteins, have been classically viewed as highly inducible, liver‐derived factors in response to infection or trauma." (PMID 32246830, 2020). "Three independent cohorts showed a strong predicted probability of KD over an infection when combining MRP8/14 and CRP." (PMID 32775314, 2020). "Common infection-related indicators of abnormalities included increased ESR (64.9%) and CRP (23.9%)." (PMID 33243228, 2020). "The aim of this prospective longitudinal study was to evaluate clinical utility of c-reactive protein (CRP), procalcitonin, and neutrophil-to-lymphocyte ratio (NLR) in surveillance of infections early after liver transplantation in intensive care setting." (PMID 32127631, 2020). "In their study, ESR and CRP performed poorly; they were found to be falsely positive (ESR 54% and CRP 21%) in cases where the infection was considered to be resolved." (PMID 32911842, 2020). "We then measured levels of erythrocyte sedimentation rate (ESR), plasma CRP and plasma LRG in these macaques at 0, 2, 4, 6, 8 and 12 weeks after infection." (PMID 32099022, 2020). "Similar to CRP, Saa and LBP are known to be induced during bacterial infections and infection with Candida species and thus these proteins seem unsuitable for differentiating between fungal and bacterial infection." (PMID 33043780, 2020). "We found that the parallel method was more reliable in the combined diagnosis of infection, and the optimal cutoff was 0.296 ng/mL and 28.13 mg/L for PCT and CRP, respectively." (PMID 30976022, 2019). "CRP in the EAP and E. coli groups was higher than that in the control and naïve groups 1 month after immunization or infection." (PMID 31088536, 2019). "Several investigations have been performed concerning the use of CRP and PCT levels for diagnosing and following up cases of infection in patients." (PMID 31691767, 2019). "Patients with a CRP/ALB ratio > 20% had a longer duration of hospitalization and higher rates of poor kidney function, infection, and re-transplantation due to graft failure, as well as higher overall mortality, than those with a CRP/ALB ratio ≤ 20%." (PMID 31821367, 2019). "C-reactive protein (CRP) is an acute-phase protein and a general marker of several pathological processes, including infection, tissue damage, cancer, and chronic inflammatory disease." (PMID 30921429, 2019). "The CRP serum levels in the EAP and E. coli groups increased a month after immunization or infection compared with the levels in the control and naïve groups." (PMID 31088536, 2019). "The overall diagnostic utility of all three inflammatory markers is similar and low, however CRP marginally outperforms ESR and PV for infections." (PMID 31208975, 2019). "In diagnosing infection, the sensitivity and specificity of PCT and CRP at the cutoff values of 0.296 ng/mL and 28.13 mg/L were relatively better than those at 0.5 ng/mL and 10 mg/L, respectively." (PMID 30976022, 2019). "Significant increase in the levels of CRP were reported in patients with H1N1 and in severe cases of infection." (PMID 30288556, 2019). "The C-reactive protein (CRP) has been identified as an inexpensive, but sensitive surrogate for infection and inflammation." (PMID 31569348, 2019). "PCT, CRP and LDH levels were significantly higher in the infection than in the control groups (P < 0.05)." (PMID 30976022, 2019). "The dynamic curves of the levels of CRP, IL-6, IL-8, IL-10, SCD163 and TNF-α in both groups demonstrated a similar trend during infection but differences between the groups was observed only in the sTREM-1 levels." (PMID 31387541, 2019). "All serologic tests presented limited values in predicting persisting infection, with the area under ROC curve of ESR, CRP, IL-6 and combination of the three markers was 57.8, 61.6, 60.3, and 62.1%, respectively." (PMID 31159792, 2019).
infection (continued). "The combined detection of serum CRP, PCT and LDH provides a new idea for diagnosis of children with malignant solid tumour and infection and further guides the clinical treatment in a better manner." (PMID 30976022, 2019). "Currently C- reactive protein (CRP) and ESR are most common biomarkers to evaluate and monitor response to treatment of inflammatory and infections." (PMID 32440298, 2019). "PCT, CRP and LDH levels were positively correlated with infection (PCT, r = 0.717, P = 0.000; CRP, r = 0.628, P = 0.000; LDH, r = 0.239, P = 0.003); PCT had the highest and LDH the lowest correlation." (PMID 30976022, 2019). "We detected PCT, CRP and LDH in serum specimens of children and investigated their correlation with infection and tumour progression." (PMID 30976022, 2019). "Serum PCT, CRP and LDH levels and positive detection rates of PCT and CRP were significantly higher (P < 0.05 and P < 0.05, respectively) in the infection than in the control groups." (PMID 30976022, 2019). "Furthermore, it remains unclear whether infection-triggered AE-IPF with high serum CRP levels has a poor prognosis; since, in most of our cases, the presence of an infectious disease was not confirmed using serum procalcitonin levels or bacterial culture tests using bronchoalveolar lavage fluid." (PMID 31086028, 2019). "C-reactive protein (CRP) is an acute inflammatory protein that expression sharply elevates under inflammation and infection conditions." (PMID 31391207, 2019). "Acute-phase reactants, such as CRP, PCT, and presepsin are a class of serum proteins that change in response to inflammation from infections, surgery, trauma, autoimmune disorders, and malignancy." (PMID 31470804, 2019). "In current study, the inflammatory indicators, WBC counts, CRP, LDH and CT scores didn’t show any difference between the two groups, implying that infection was similar between the two groups." (PMID 31727051, 2019). "The ROC curve of PCT combined with CRP in diagnosing infection, LDH combined with CRP in diagnosing tumour progression, and the combination of three indices in diagnosing infection with tumour progression were drawn, respectively." (PMID 30976022, 2019). "Analysis indicated that their PCT, CRP and LDH levels were positively correlated with infection (PCT, r = 0.717, P = 0.000; CRP, r = 0.628, P = 0.000; LDH, r = 0.239, P = 0.003), with PCT and CRP having a relatively high and LDH a relatively low correlation." (PMID 30976022, 2019). "Out of these, two were classified aseptic, although definitive histology indicated a low-grade infection (according to Krenn classification type III), and the serum CRP-level was elevated." (PMID 30191275, 2019). "To avoid the influence of infection factors, we performed ROC curves on PCT, CRP and LDH in the control group." (PMID 30976022, 2019). "Analysis of these results indicated that PCT and CRP had significantly higher values than LDH in diagnosing infection, and LDH and CRP also had significant advantages in judging tumour progression." (PMID 30976022, 2019). "We compared the diagnostic value of procalcitonin (PCT), C-reactive protein (CRP) and lactate dehydrogenase (LDH) in paediatric malignant solid tumour concurrent with infection and tumour progression." (PMID 30976022, 2019). "The two most prominent proteins, CRP and PCT, are used as routine markers in clinical practice, but their use as inflammation and infection markers and as possible markers for the clinical success of the antibiotic treatment is still controversial." (PMID 31419260, 2019). "The major acute phase proteins Alpha-1 antitrypsin (A1AT) members 1 and 3, Haptoglobin, Hemopexin, Alpha-1 acid glycoprotein, CRP, and SAA2 reached comparable maximum fold change values at the common post-infection time-points between the infection types." (PMID 30774579, 2019).
infection (continued). "White blood cell (WBC) count, C-reactive protein (CRP), and erythrocyte sedimentation rate (ESR) should be obtained, and their elevation, especially when combined, is a strong predictor of infection." (PMID 30595922, 2018). "As with THA of any type, complete workup of symptomatic MoM THA would include laboratory values to exclude infection, such as ESR, CRP, and CBC with differential." (PMID 29607251, 2018). "Circulating C-reactive protein (CRP) is a key acute-phase protein and one of the main clinical biomarkers for inflammation and infection." (PMID 29892284, 2018). "Therefore, we consider the majority of elevated CRP values to be a result of the underlying cancer even though it cannot be completely ruled out that infection may be the accountable reason in some of the cases." (PMID 29534089, 2018). "We assessed C-reactive protein (CRP), procalcitonin, and neutrophil lymphocyte ratio (NLR) as indicators of infection/inflammation." (PMID 30234089, 2018). "Finally, a number of studies have considered the utility of combined biomarkers, such as CRP with interleukin-6 (Il-6) in periprosthetic joint pathology showing superiority over other biomarkers (including procalcitonin) when distinguishing between aseptic joint loosening and infection [35•, 36]." (PMID 30225546, 2018). "First, a delayed sampling in the course of infection, possibly suggested by the time elapsed between the onset of clinical signs determined retrospectively and the timing of sampling, could explain the better performances of CRP, which rises in the circulation 8–12 h after the onset of infection." (PMID 30542642, 2018). "Our study found that IG percentage is a useful marker to predict the severity of infection and it adds information to the conventional infection markers WBC, ANC, and CRP for the early identification of pediatric patients with SBI." (PMID 30344287, 2018). "Among the molecules identified, C-reactive protein (CRP) is an acute-phase protein secreted from the liver in response to inflammation, infection, and tissue damage." (PMID 30395577, 2018). "C-reactive protein and PCT are the two most investigated and widely used biochemical markers, which are already being used in the clinical practice to evaluate the infections." (PMID 30675399, 2018). "Logistic regression analysis was done for statistically significant variables suggestive of infection including fever, abdominal pain or tenderness, elevated TLC, ANC and CRP." (PMID 30289914, 2018). "It was assumed that this test would be used effectively in diagnosing early postoperative infection with the combination of the ESR and CRP." (PMID 29439725, 2018). "C-reactive protein (CRP), a marker for systemic inflammation, is produced by the hepatocytes upon inflammation, infection, or tissue injury." (PMID 30619885, 2018). "During the first hospitalization, the patient presented with an infection of strain XNO62, distinguished by high levels of WBC, Neu%, CRP, and ESR values." (PMID 30013523, 2018). "Additionally, we also measured serum HP antibody and pepsinogen levels, which directly reflect current/former chronic inflammation of the gastric mucosa due to infection, and investigated their association with global methylation levels with and without adjustment by CRP concentration." (PMID 29439678, 2018). "We expected that the CD64 index would have a more significant advantage in the diagnosis of infection than the WBC and CRP." (PMID 29968788, 2018). "The reference levels of CRP and ESR have been criticized because of their low specificity for diagnosing infections." (PMID 29854731, 2018). "Hence, we speculate that CRP predominantly inhibits trauma-associated release of IL-1β without preventing the IL-1β response to infection." (PMID 30105015, 2018). "By comparing the ROC curves of CD64 and the traditional infection indices in the infected group, we found that the AUC of the CD64 index was greater than that of the WBC and CRP." (PMID 29968788, 2018).
infection (continued). "Changes in many clinical indicators (e.g., WBC, RBC, hemoglobin, hematocrit, CRP, and NLR) were observed for patients with infection (N = 32)." (PMID 30125325, 2018). "C-reactive protein (CRP) is an acute phase reactant, commonly used to evaluate infection, tissue injury and inflammation." (PMID 28785075, 2017). "A set of blood tests including C-reactive protein (CRP), Erythrocyte Sedimentation Rate (ESR) and white cell count (WCC) is essential to exclude infection." (PMID 29290860, 2017). "The American Association of Orthopaedic Surgeons (AAOS) recommends erythrocyte sedimentation rate (ESR) and C-reactive protein (CRP) as baseline investigations with selective use of aspiration and biopsy for patients with a higher probability of infection." (PMID 29290857, 2017). "C-reactive protein (CRP) is an indicator of inflammatory processes and its levels rise in response to surgical procedures or infection." (PMID 28069040, 2017). "The serum biochemistry exhibited elevated levels of white blood cells (WBC) and C-reactive protein (CRP) (11300/μL and 5.37mg/dL, respectively), indicating the possibility of an infection." (PMID 28379669, 2017). "The optimized cut-offs for infection diagnosis for GM-CSF and TNF-α produced higher sensitivities and specificities versus CRP, HS-CRP, and PCT." (PMID 28264059, 2017). "C-reactive protein (CRP), as an acute phase protein from liver cells, has been used clinically to monitor infection and autoimmune disorders." (PMID 28464873, 2017). "C-reactive protein (CRP) is an acute phase protein produced and released in the circulation in response to infection and tissue damage." (PMID 28813455, 2017). "This is an extremely important fact because it emphasizes the importance of CRP, ESR, and PCT for the diagnosis of early infections by showing suspicious markers which enable the orthopedic surgeon to implement the best diagnostic-therapeutic protocol." (PMID 29138696, 2017). "Further studies are needed to clarify route of infection, role of PCT and CRP, and optimal therapy including drug and duration." (PMID 28596927, 2017). "Other studies with comparisons between CRP concentrations and the “quick” SOFA criteria are needed to prompt clinicians to further evaluate patients for the presence of infection and/or organ dysfunction." (PMID 28226029, 2017). "C-reactive protein (CRP) is an acute-phase reactant, synthesized primarily in the liver and released into the blood in response to tissue injury or infection." (PMID 28477314, 2017). "This is expected considering the fact that the proliferation and introduction of immature neutrophils into the circulation occurs during the earliest phase of stress or infection before the total WBC count, ESR and CRP increases." (PMID 28169298, 2017). "Commonly used biomarkers such as CRP and WCC are markers of inflammation and can be raised indiscriminately in pro-inflammatory states such as malignancy and infection." (PMID 28158976, 2017). "On the 4th day of hospitalization, the patient's infection improved with a dropped temperature (37.2°C), WBC (9.2 × 103/μL), and CRP (58 mg/L)." (PMID 29245350, 2017). "C-reactive protein (CRP), as an acute phase protein from liver cells, has been regarded as an early indicator of infection and autoimmune disorders." (PMID 28582961, 2017). "On the 3rd day of hospitalization, the patient's infection exacerbated with an elevated white blood cell count (WBC) of 19.1 × 103/μL, C-reactive protein (CRP) of 68 mg/L and a high temperature of 40°C." (PMID 29245350, 2017). "Our results indicate that CRP is a better biomarker than WBC and ANC in guiding diagnosis of infections among children with acute febrile illness, especially in infections of bacterial origin." (PMID 28451028, 2017). "Are the C-reactive protein (CRP), the erythrocyte sedimentation rate (ESR), and procalcitonin (PCT) good markers for THA infection screenings?" (PMID 29138696, 2017).